KEAP1 (kelch like ECH associated protein 1)
Diseases named in the same sentence as KEAP1 in open-access papers (continued):
Sharing a sentence is not in itself a finding about the gene and the disease.
lung adenocarcinoma (continued). "Interestingly, KEAP1 is the third most frequently mutated gene in lung adenocarcinoma (LUAD) and often co-occurs with oncogenic mutations in KRAS." (PMID 28967864, 2017). "The findings of these authors suggest that RSPO3 overexpression may potentially act as a driving mechanism behind the aggressiveness of Keap1-deficient lung adenocarcinomas." (PMID 27980454, 2016). "RSPO3 was reported to promote tumor aggressiveness in Keap1-deficient lung adenocarcinomas." (PMID 27980454, 2016). "Similarly, loss of Keap1 in lung adenocarcinoma patients is associated with high-grade and late-stage disease and shortened survival, which might be caused by an increased rate of metastasis in these patients." (PMID 35534896, 2022). "Taken together, our data suggests that glutaminase is an attractive target in both lung adenocarcinoma and in other cancers in which the KEAP1/NRF2 axis is mutated and the glutaminase inhibitor CB-839 could be an effective therapeutic agent in patients with these genetic subtypes of cancer." (PMID 28967864, 2017). "In this study, we used multi-omics and wet-lab approaches to explore the correlation between KEAP1 mutations, the methylation status of the NR0B1 promoter, NR0B1 gene expression and survival of patients with lung adenocarcinoma (LUAD)." (PMID 40864301, 2025). "In human lung adenocarcinoma, the extent of KEAP1 inactivation likely varies by patient, with both partial and complete KEAP1 inactivated mutants existing." (PMID 41462606, 2025). "The immunosuppressive microenvironment in KEAP1-mutant lung adenocarcinoma presents a promising target for triterpenoid derivatives to enhance anti-cancer immune functions." (PMID 41462606, 2025). "The KEAP1-mutant human lung adenocarcinoma parental cell line (A549) and its derived cisplatin-resistant cell line (A549/DDP) were selected as in vitro cell models to study cisplatin resistance." (PMID 40544155, 2025). "Two lung adenocarcinoma patients with KEAP1 received standard therapy of albumin paclitaxel + carboplatin + Coreda for 3 months after tumour proportion score (TPS) of PD-L1 Immunohistochemical test showed 95% and 90% respectively (Figure 7A1,A2)." (PMID 38962454, 2024). "A549 lung adenocarcinoma cells overexpressing mutant KEAP1 showed high TRAF2-mediated NFκB activity and increased protection against apoptosis, XIAP being one of the key proteins involved in anti-apoptotic signalling." (PMID 38184997, 2024). "In contrast, LCNEC II exhibits alterations in NSCLC-type serine/threonine kinase 11 (STK11), Kelch-like ECH-associated protein 1 (KEAP1), and Kirsten rat sarcoma virus (KRAS); these are commonly seen in lung adenocarcinomas too." (PMID 38693435, 2024). "Out of the key genes that drive multiple immune traits, top hit KEAP1 in lung adenocarcinoma (LUAD) was selected for validation." (PMID 38241355, 2024). "Of these, KEAP1 was identified as the top hit in lung adenocarcinoma (LUAD) and explained a large proportion (>10%) of variance for multiple immune traits, including interferon pathway, MHC class II expression, and the NK cell signature score." (PMID 38241355, 2024). "KRAS mutation, a common driver of lung adenocarcinoma, is associated with KEAP1 loss-of-function mutations in approximately 20% of KRAS mutant NSCLC cases, forming a KRAS-KEAP1 co-mutation (KK) type." (PMID 38566036, 2024).
lung adenocarcinoma (continued). "FDA-emerging biomarkers were present in both histologies, with genes like STK11, KEAP1, and others more frequently altered in lung adenocarcinoma." (PMID 39664186, 2024). "The genes whose loss is predicted to be detrimental to EGFR-driven tumors (i.e., Keap1, Lkb1, and Nf2) are rarely co-mutated with EGFR in human lung adenocarcinoma as predicted." (PMID 37828026, 2023). "For example, hsa_circRNA_102442 (circKEAP1) derived from exon 2 of the KEAP1 gene is downregulated in lung adenocarcinoma tissues in comparison to adjacent normal tissues." (PMID 37511619, 2023). "This study showed KEAP1 inactivation as a prominent resistance mechanism of osimertinib in lung adenocarcinoma." (PMID 38169973, 2023). "Lung adenocarcinoma has higher frequencies of KRAS, EGFR, KEAP1, STK11, MET, and BRAF somatic mutations." (PMID 38130901, 2023). "The use of CRISPR/Tuba-seq indicated that KEAP1 inactivation considerably diminished the sensitivity of EGFR-driven lung adenocarcinoma to the EGFR inhibitor osimertinib in a TSGs pool." (PMID 38169973, 2023). "Compared with the wild-type samples, lung adenocarcinoma harboring KEAP1/NFE2L2 had a significantly lower lymphocyte fractions (P = 0.001)." (PMID 35371318, 2022). "A recent research implicated that the diversity of KRAS-mutant lung adenocarcinomas (LUADs) is associated with different characters, such as KRAS dependency, immunogenicity, and STK11/KEAP1 comutations." (PMID 35945957, 2022). "Specifically, proteomic profiles of 47 lung adenocarcinoma (LUAD) cell lines (11 KEAP1 mutant and 36 KEAP1 wild-type) revealed the tryptophan-kynurenine enzyme kynureninase (KYNU) as a top overexpressed protein associated with activated NRF2." (PMID 35626147, 2022). "The KEAP1/NFE2L2 mutations, representing the dysfunctional activations of the stress response pathway, have been found in many malignant tumors, including lung adenocarcinoma 19-21." (PMID 35371318, 2022). "As previously stated in the Methods section, we integrated five data subtypes and clustered 89 KEAP1/NFE2L2-mutant lung adenocarcinoma patients into two subgroups (P1 and P2 groups)." (PMID 35371318, 2022). "There is a report that the therapeutic effect of programmed death-(ligand) 1 (PD-1/PD-L1) inhibition was diminished in STK11- and KEAP1-mutant lung adenocarcinoma." (PMID 36107353, 2022). "The initial results were validated by using in silico assessment of common lung adenocarcinoma cell lines, which revealed consistent features of KEAP1/NFE2L2-mutant subtypes." (PMID 35371318, 2022). "In lung adenocarcinoma cells, it has been reported that Keap1–Nrf2 interactions suppressed cell motility by targeting S100P15." (PMID 33441941, 2021). "The immunohistochemistry for KEAP1 protein in 105 paired lung adenocarcinoma tumor tissues was performed to analyze the protein level of KEAP1." (PMID 34136401, 2021). "These correlations were then extended to TCGA analysis of 517 lung adenocarcinoma patients, out of which 35% showed elevated PTGR1, and 40% of those further displayed statistically significant co-occurrence of KEAP1 mutations." (PMID 33889302, 2021). "Kelch‐like ECH‐associated protein 1 (KEAP1) has been identified as a cancer driver gene in lung adenocarcinoma (LUAD), and increased evidence has given us clues about the association of KEAP1 mutation and immune characteristics." (PMID 34328274, 2021). "Here we aim to clarify the effect of Keap1 on the biological characteristics and chemotherapy resistance in lung adenocarcinoma (LUAD)." (PMID 34466284, 2021). "Consistent with the results of immunohistochemistry, the Western blotting for KEAP1 protein in 12 paired lung adenocarcinoma tumor tissues and adjacent normal tissues also confirmed that the protein level of KEAP1 was significantly downregulated." (PMID 34136401, 2021). "For example, in lung adenocarcinoma (LAC) cohorts, patients who carried mutations in the KEAP1/NFE2L2 pathway had significantly shorter survival." (PMID 33109073, 2020).
lung adenocarcinoma (continued). "For instance, the prognostic in lung adenocarcinoma LncRNA1 (PILAR1), a new prognostic lncRNA, is associated with a high mutation rate of Kelch-like ECH-associated protein 1(KEAP1)." (PMID 32445554, 2020). "For example, combining clinical data and in vivo and in vitro approaches revealed the importance of KEAP1 and NFE2L2 mutations in lung adenocarcinoma, correlating them with advanced stages and worse survival." (PMID 33228209, 2020). "We infer that FGL2 affects the KEAP1 effect by influencing immune status in tumor environment of lung adenocarcinoma." (PMID 32206449, 2020). "Alterations in KEAP1/ NF-E2 p45-related factor 2 (NFE2L2/Nrf2) signaling pathway have been reported in 23% lung adenocarcinoma patients, suggesting that deregulation of the pathway is a major cancer driver." (PMID 31811110, 2019). "Decreased NRF2 activity reduces trophoblast invasion in placenta 66, and KEAP1 overexpression suppresses migration of lung adenocarcinoma cells." (PMID 31668005, 2019). "The pilot study demonstrated a VNR-sensitive strategy in lung adenocarcinoma cells, by which regulators of autophagy modulated Keap1-mediated ROS generation and VNR-induced apoptosis." (PMID 30245856, 2018). "Some genes significantly mutated were exclusively mutated in lung adenocarcinoma, such as STK11 (LKB1), RBM10, KEAP1, RIT1 and MET, while other genes such as NFE2L2, KDM6A, RASA1, NOTCH1 and HRAS are significantly mutated in LSQCC." (PMID 30060526, 2018). "Lung adenocarcinomas bearing ERBB2/3 alterations, ROS mutations and KEAP1 inactivation are also susceptible of targeting therapies." (PMID 30060526, 2018). "According to these findings, autophagy regulates vinorelbine sensitivity by continuing Keap1-mediated ROS generation in lung adenocarcinoma cells." (PMID 30245856, 2018). "(e) Western blot depicting Nrf2 expression in KEAP1 wild type human lung adenocarcinoma line (H2009) after treatment with KI696." (PMID 28967864, 2017). "Examples were NSD1 in HNSC, CTNNB1 in liver hepatocellular carcinoma (LIHC), and STK11 and KEAP1 in lung adenocarcinoma (LUAD)." (PMID 29125844, 2017). "FBN2 disruption precedes the subclonal deletion of genes along chromosome 9p, including significantly mutated known lung adenocarcinoma genes SMARCA4, KEAP1, and STK11." (PMID 25160065, 2014). "Therefore, we acknowledge that the regulatory landscape of NR0B1 is multifactorial, and further studies are warranted to dissect these alternative regulatory mechanisms in the context of KEAP1-mutant lung adenocarcinoma." (PMID 40864301, 2025). "STK11 and KEAP1 mutations were associated with worse outcomes to immunotherapy in KRASmut but not in KRASwt lung adenocarcinoma." (PMID 38866964, 2024). "Our analysis suggests that designing a MSLN-directed ADC carrying eribulin mesylate as a payload may be beneficial for STK11/KEAP1-mutant lung adenocarcinoma patients." (PMID 39186767, 2024).
lung adenocarcinoma (continued). "Patients with STK11/KEAP1-mutant lung adenocarcinoma may experience limited benefit from checkpoint blockade therapies highlighting unmet need for improved treatment strategies." (PMID 39186767, 2024). "Notably, the KEAP1 gene in lung adenocarcinoma (LUAD) emerged as a key player, explaining over 10% of immune trait variations." (PMID 38241355, 2024). "Loss-of-function Kelch-like ECH-associated protein 1 (KEAP1) mutations or gain-of-function nuclear factor erythroid 2-related factor 2 (NFE2L2; also known as NRF2) mutations are found in ~20% of lung adenocarcinoma (LUAD) and in ~30% of lung squamous cell carcinoma (LUSC)." (PMID 38536921, 2024). "CircKEAP1 suppresses the progression of lung adenocarcinoma via the miR-141-3p/KEAP1/NRF2 axis." (PMID 37686043, 2023). "Consistent results were observed in the lung adenocarcinoma (LUAD) patient cohort, where the NRF2 pathway and nuclear receptor metapathway, which encompass the majority of NRF2 target genes, were significantly upregulated in KEAP1-mutated samples." (PMID 37633973, 2023). "Interestingly, somatic mutations in NLRP3 together with 10 other genes including KEAP1, KRAS, and STK11 were reported to define a molecular signature associated with a subtype of NSCLC, the lung adenocarcinoma (LUAD)." (PMID 36746533, 2023). "Activation of the nuclear factor erythroid 2-related factor 2 (NRF2) pathway, either through gain-of-function mutation or loss-of-function of its suppressor, Kelch-like ECH-associated protein 1 (KEAP1), is one of the most dysregulated pathways in lung adenocarcinoma (LUAD)." (PMID 35626147, 2022). "The study explored intrinsic heterogeneities of KEAP1/NFE2L2-mutant lung adenocarcinoma." (PMID 35371318, 2022). "Hence, SCD1 is a promising candidate for targeted drug development in STK11/KEAP1 co-mutant lung adenocarcinoma and ameliorated the drug resistance by inducing ferroptosis." (PMID 36439884, 2022). "Nuclear translocation of NRF2 due to loss of KEAP1 expression by biallelic inactivation of the gene via mutation, loss of heterozygosity or promoter methylation has been shown to frequently occur in KRAS mutant lung adenocarcinoma." (PMID 35626147, 2022). "In lung adenocarcinoma (LUAD), serine/threonine kinase 11 (STK11) and Kelch-like ECH-associated protein 1 (KEAP1) co-mutant status strongly predict poor survival, which is associated with significantly elevated ferroptosis-protective gene expression and less vulnerability to ferroptosis." (PMID 35399527, 2022). "The biological features and intrinsic heterogeneities of KEAP1/NFE2L2-mutant lung adenocarcinoma remain unclear." (PMID 35371318, 2022). "It has been reported that TTF‐1 negative lung adenocarcinoma had more frequent Kelch‐like epichlorohydrin‐associated protein 1 (KEAP1) mutations, which negatively affect ICI efficacy, than TTF‐1 positive lung adenocarcinoma." (PMID 35808895, 2022). "Since KEAP1/NFE2L2/CUL3 gene mutations have not received enough attention in the clinical practice of lung adenocarcinoma, these three genes are not included in routine postoperative pathologic sample gene mutation detection in our hospital." (PMID 34617407, 2021).
lung adenocarcinoma (continued). "Indeed, EGF expression correlated with NRF2 activation in different cancer types, as we showed for NFE2L2/KEAP1 mutant lung adenocarcinoma as well as head and neck squamous cell carcinoma." (PMID 33916908, 2021). "In lung adenocarcinoma, KEAP1 and STK11 mutations are associated with the non-T cell-inflamed phenotype." (PMID 33106165, 2020). "In this current study, we carried out an integrated, multi-omics, multi-database analysis of exome, transcriptomics data's of KEAP1 mutated TCGA- Lung adenocarcinoma (LUAD) patients against non-mutated counterparts." (PMID 31839815, 2019). "Co-mutation of KRAS with loss of KEAP1 (kelch like ECH associated protein 1) further extended the glycolytic phenotype, dependence on glutamine, and sensitivity to glutaminase inhibitors in lung adenocarcinoma models." (PMID 31681559, 2019). "In lung adenocarcinomas there is a trend toward co-mutation of KRAS and KEAP1." (PMID 31581742, 2019). "The high expression of Keap1 was not significantly correlated with gender, age, smoking, differentiation, subtype of lung adenocarcinoma and status of EGFR gene mutation (P > 0.05)." (PMID 29587953, 2018). "Importantly, KEAP1/KRAS-mutant lung adenocarcinomas are dependent upon increased glutaminolysis and are therapeutically sensitive to pharmacologic inhibition of glutaminase." (PMID 30060526, 2018). "The aim of this study is to investigate the protein expression level of Nrf2 and Keap1 in lung adenocarcinoma and to elucidate the correlation between Nrf2 or Keap1 expression and the status of EGFR gene mutation and to determine the effects of Nrf2 and Keap1 on the patients." (PMID 29587953, 2018). "Type I and II LCNECs harbor key genomic alterations and oncogenic mutations, which are commonly found in SCLC, lung adenocarcinoma or squamous cell carcinoma (e.g., in RAS genes, BRAF, NFE2L2, as well as in STK11 and KEAP1 in the case of type I LCNECS, and RB1 losses in the case of type II LCNECs)." (PMID 29535388, 2018). "Therefore, in order to explore the potential biomarkers in KEAP1/NRF2 mutated NSCLC, we performed integrated multi-omics approach by using A549 NSCLC cell lines and TCGA lung adenocarcinoma patients data." (PMID 29050246, 2017). "It is known that multiple KEAP1 missense mutations occur in human lung adenocarcinoma and they are not limited in certain domains but widely distributed throughout KEAP1." (PMID 27340506, 2016). "Additionally, molecular profiling of lung adenocarcinoma has identified a high frequency of mutations in the tumor suppressors serine threonine kinase 11 (STK11–17%) and Kelch-like ECH associated protein 1 (KEAP1 - 17%), based on the analysis of 230 samples from the TCGA database." (PMID 39955067, 2025). "STK11 and KEAP1 co-mutated lung adenocarcinoma, which are associated with aggressive tumor growth and immunotherapy resistance, had higher repstress scores compared with lung adenocarcinoma without concomitant loss of these genes." (PMID 36381660, 2022). "Interestingly, Best and colleagues showed that murine models of lung adenocarcinoma harboring KRAS and LKB1 mutations exhibit increased glutaminase expression by tumor cells and increased glutamate in the tumor microenvironment, compared to KRAS mutant/KEAP1 mutant lung adenocarcinomas." (PMID 40255421, 2025). "Proteomic profiles of 47 lung adenocarcinoma (LUAD) cell lines (11 KEAP1 mutant and 36 KEAP1 wild-type) revealed the tryptophan-kynurenine enzyme kynureninase (KYNU) as a top overexpressed protein associated with activated NRF2." (PMID 35626147, 2022).